MYO15A (myosin XVA)
Diseases named in the same sentence as MYO15A in open-access papers (continued):
Sharing a sentence is not in itself a finding about the gene and the disease.
deafness (continued). "In this study, 48.5% (16/33) families were detected the pathogenic variants in eight known deafness genes, including 10 novel variants identified in TMPRSS3 (MIM 605551), MYO15A (MIM 602666), TMC1 (MIM 606706), ADGRV1 (MIM 602851), and PTPRQ (MIM 603317)." (PMID 31379920, 2019). "By comparing different ethnic groups, the MYO15A is considered to be the third most common deafness gene, and all domains and motifs of protein coding sequence by MYO15A gene have been identified." (PMID 31250571, 2019). "We discovered that four MYO15A pathogenic variants in the motor and FERM domains caused partial deafness with significant residual hearing at low frequencies." (PMID 29482514, 2018). "In this study, we used NGS technology, which led to the identification of novel alleles in SLC26A4, MYO15A, OTOG, LOXHD1, and TBC1D24 that are associated with deafness." (PMID 30139988, 2018). "Homozygous p.C1779Y mutation in the Myo15 gene, a murine homologue of the human MYO15A gene, cause profound sensorineural deafness, vestibular defects, and extremely short stereocilia on the inner and outer hair cells in shaker-2 mice." (PMID 26308726, 2015). "There were also three probands (SHJ3, SHJ16, and SNUH53-118) with only one definitely pathogenic mutant allele in one of three recessive deafness genes, OTOA, MYO15A, and MYO7A, respectively." (PMID 25373420, 2014). "In the present study 53% (16/30) of the families were found to carry causative mutations in GJB2 illustrating that the most frequently involved gene in deafness in the Pakistani population is GJB2 followed by MYO15A (13%, 4/30) and TMC1 (10%, 3/30)." (PMID 24949729, 2014). "Then we compared these variants to reported nonsyndromic hereditary hearing loss genes; 2 mutations (c.IVS25 + 3G > A, c.8375 T > C) were found in a previously reported deafness-related gene, MYO15A." (PMID 24206587, 2013). "Mutations in SLC26A4, MYO15A, and CDH23 are also reported to be frequent and important causes of deafness." (PMID 23967202, 2013). "Three of them, p.R2728H in MYO15A, p.R445H and c.150delT in TMC1, have been previously reported to be associated with non-syndromic deafness." (PMID 23767834, 2013). "SR-285 carried three candidate variants of known deafness genes (p.Q445R in GRHL2, p.T1321S in TECTA, and p.S2161F in MYO15A); only one mutation, p.S2161F in MYO15A, was shared with an affected sibling." (PMID 23865914, 2013). "Notably, the prevalence of MYO15A-related deafness exhibits variability based on the ethnicity and country of the study population." (PMID 38167320, 2024). "MYO15A is an autosomal recessive deafness gene located on the human chromosome 17p11.2." (PMID 34609590, 2022). "We identified four variants in MYO15A, two novel variants never previously linked to deafness (c.7212+5G>A and p.Leu2532ArgfsTer37) and two recurrent variants (p.Tyr2684His and p.Gly3287Gly)." (PMID 34733312, 2021). "The known deafness genes with variants detected in this study were GJB2 (MIM 121011; 21.2%), TMPRSS3 (MIM 605551; 6.1%), MYO15A (MIM 602666; 6.1%), TMC1 (MIM 606706; 3%), ADGRV1 (MIM 602851; 3%), PTPRQ (MIM 603317; 3%), SLC26A4 (MIM 605646; 3%), and OTOF (MIM 603681; 3%)." (PMID 31379920, 2019). "MYO15A, a causative gene of DFNB3 (OMIM 600316), is a frequently detected deafness gene." (PMID 29482514, 2018). "Changes in the MYO15A gene are known to be responsible for DFNB3 deafness." (PMID 29849560, 2018). "Cochlear implantation has been reported to offer satisfactory auditory performance to patients with severe to profound deafness caused by mutations in the GJB2 gene, the solute carrier family 26 member 4 gene (SLC26A4), the otoferlin gene (OTOF), or the myosin XVa gene (MYO15A)." (PMID 26308726, 2015). "The biallelic sequence variants predicted to be the causative mutations in the patients are all located in genes already known to be involved in deafness (MYO15A, TMC1 and LRTOMT), but these particular mutations have not been previously reported." (PMID 24926664, 2014).
deafness (continued). "In the current study MYO15A was found to be the second leading cause of deafness in the Pakistani population, but still no recurrent mutation was identified in this gene." (PMID 24949729, 2014). "The most frequent causative deafness gene was TMC1 (DFNA36) (3 cases), followed by the next tier of genes (2 cases each) (CDH23, COCH, SLC26A4, TMPRSS3, ATP1A3), and the genes that were detected only once (ACTG1, GJB2, ILDR1, MYO7A, MYO15A, NF2, NLRP3 and SERPNB6)." (PMID 32238869, 2020). "Despite the genetic heterogeneity, some genes showed greater contribution to cases of autosomal recessive deafness in our study: GJB2, CDH23 (10.34%), MYO15A (7%), OTOF (7%), and USH2A (7%)." (PMID 39498320, 2024). "Among the 98 deafness-related genes detected in this study, SLC26A4 (62.7%, 32/51), MYO15A (63.6%, 14/22), OTOF (40.0%, 4/10) and PTPRQ (75.0%, 3/4) contained intronic variants." (PMID 36597107, 2023). "The most frequent causative gene revealed by this technology was CDH23 (n = 3), followed by MYO15A (n = 2), MYO7A (n = 2) and other four deafness genes (PCDH15 (n = 1), USH2A (n = 1), MYO3A (n = 1) and ACTG1 (n = 1))." (PMID 25373420, 2014). "TMPRSS3, MYO15A, GJB2, SLC26A4 were found to be responsible for deafness in autosomal recessive or sporadic families." (PMID 23967202, 2013). "The most prevalent deafness genes identified in our cohort include SLC26A4 (22%), GJB2 (13%), MYO15A (6%), and OTOF (6%); whereas those identified in the American patients were GJB2 (36%), SLC26A4 (13%), MYO7A (8%), and MYO15A (8%)." (PMID 36009393, 2022). "With regard to the responsible gene, the most frequent causative gene was GJB2 (29%), followed by SLC26A4 (9%), CDH23 (7%), MYO7A (4%), OTOF (5%), MYO15A (3%), and LOXHD1 (2%), indicating that these deafness genes are typical deafness genes found in the prelingual CI/EAS patients." (PMID 32027099, 2020). "As many of the known genes associated with recessive HI were not tested, several of which are commonly involved (e.g. MYO15A), defects in other deafness genes cannot be excluded in the reported case." (PMID 30535804, 2019). "In the current study, three known deafness genes (GJB2, TMPRSS3, and MYO15A) were detected in several pedigrees, suggesting that the strategy of proband-WES can be successfully applied to search for novel ARNSHL genes shared by multiple families with similar phenotype." (PMID 31379920, 2019). "Thus, through this analysis, the molecular etiology of deafness was confirmed in 23.56% (90/382) of the patients, and it involved the GJB2, SLC26A4, CDH23, MYO15A, and MT-RNR1 genes." (PMID 27018795, 2016). "TMPRSS3, MYO15A, GJB2, SLC26A4 were found to be responsible for deafness in autosomal recessive or sporadic families, while TECTA, WFS1, MYH9, EYA1, COL4A5 and COL11A1 were identified as the responsible genes for deafness in autosomal dominant families." (PMID 23967202, 2013).
hearing loss (51 papers, 2010 to 2025). "Our work shows that in addition to generating force and motility, the ATPase domain of MYO15A can directly regulate actin polymerization and that disrupting this activity can promote cytoskeletal disease, such as hearing loss." (PMID 39843411, 2025). "Mutations in MYO15A are currently the third most common cause of hearing loss, with ~192 mutations identified to date." (PMID 39482536, 2024). "Two genes encoding conventional myosins, MYH9 and MYH14, and four genes encoding unconventional myosins, MYO3A, MYO6, MYO7A and MYO15A, are associated with nonsyndromic hereditary hearing loss in human." (PMID 38562617, 2024). "Individuals with hearing impairment resulting from a variant in the MYO15A gene typically derive advantages from Cochlear transplantation." (PMID 38167320, 2024). "Variants in the MYO15A gene have been identified as a causative factor for sensorineural hearing loss in humans, specifically in cases of autosomal recessive 3 (OMIM, #600,316)." (PMID 38167320, 2024). "At that time, it was considered that the phenotype of the hearing loss in cases with MYO15A variants was closely related to the region where this gene variant was located." (PMID 35346193, 2022). "We investigated the association of MYO15A variants with the severity, progression and age of onset of hearing loss, as well as compared it to the previous reports in different nationalities." (PMID 35346193, 2022). "According to the guidelines of the ACMG/AMP on hereditary hearing loss, the variations in the MYO15A were manually classified." (PMID 35346193, 2022). "Our results further indicate that MYO15A-associated hearing loss is good candidates for cochlear implantation, which is in accordance with previous report." (PMID 36401330, 2022). "This knowledge will also be vital for any future gene therapies targeting MYO15A related hearing loss or the p.Gly3287Gly variant specifically." (PMID 34733312, 2021). "The proband underwent genetic testing using a high-throughput NGS panel for 60 known pathogenic variants that cause hearing loss, which revealed a heterozygous missense variant in MYO15A (c.8050T>C; p.Tyr2684His)." (PMID 34733312, 2021). "With the extensive application of next generation sequencing, genetic diagnosis is playing a more important role in the prenatal diagnosis and clinical evaluation of MYO15A-associated hereditary hearing loss." (PMID 30068307, 2018). "In the present study, we show that MYO15A can directly stimulate actin filament nucleation in vitro, and that nucleation is inhibited by the jordan (p.D1647G) mutation that stunts stereocilia growth and causes hearing loss in vivo." (PMID 39843411, 2025). "Therefore, it is crucial to comprehensively analyze the variant spectrum of the MYO15A gene in each country for the diagnosis and prevention of hearing loss." (PMID 38167320, 2024). "Clinically, variants in MYO15A have been found to result in congenital severe to profound hearing loss across all frequencies, although some patients may retain residual hearing at lower frequencies." (PMID 38167320, 2024). "Although, variants in MYO15A lead to variable hearing impairment phenotype, from mild to severe, splice-site variants have been linked to a severe hearing loss phenotype in all identified cases, except those hearing loss degrees were not described in the literatures." (PMID 36401330, 2022). "Mutations of the MYO15A gene are the third most common cause of hereditary hearing loss." (PMID 34093702, 2021). "GJB2, SLC26A4, and MYO15A are the top three common genes responsible for hereditary hearing loss." (PMID 34093702, 2021). "Notably, p.(Phe3420del) in MYO15A has been reported in hearing loss patients from the Chinese Han population." (PMID 30682115, 2019).
hearing loss (continued). "Interestingly, recent studies have reported that some variants of MYO15A affecting the function of other domains, which were expected to bring about congenital severe to profound hearing loss, also were observed to result in various milder auditory phenotypes." (PMID 30953472, 2019). "Therefore, for every country, consummating its own MYO15A mutation spectrum is essential for the diagnosis and prevention of hearing loss." (PMID 29849560, 2018). "Results revealed exon skipping in the message of MYO15A c.9083+6T>A, and intron retention in the message of MYO15A c.8340G>A, in each case leading to a premature stop and consistent with co-segregation of homozygosity for each variant with hearing loss." (PMID 30139988, 2018). "Specifically, pathogenic variants in the N-terminal domain of MYO15A have been suggested to be associated with residual hearing, especially at low frequencies, while pathogenic variants in other domains resulted in congenital severe-to-profound hearing loss." (PMID 29482514, 2018). "Additionally, two newly identified mutations (e.g., p.Q3172X/p.V2632L) of MYO15A were noticed in the J07 family, and the subjects presented severe hearing loss." (PMID 29692870, 2018). "However, recently, some families suffering from less severe hearing impairment were also diagnosed a genetic cause of MYO15A mutations." (PMID 29849560, 2018). "A milder phenotype may have been influenced by factors like milder pathogenic potential from hypomorphic alleles of MYO15A, genetic modifiers that reduce severity of hearing loss, or environmental factors." (PMID 29482514, 2018). "To date, a number of mutations in MYO15A gene have been identified in hereditary hearing loss." (PMID 29849560, 2018). "However, a strategy for screening other hearing loss genes is difficult, and Sanger sequencing of candidate genes with multiple exons, such as MYO15A, is time-consuming." (PMID 23865914, 2013). "In addition to these causative mutations, 12 nonsynonymous variants were identified in the MYO15A coding exons from 17 hearing-loss patients and 30 Korean control exomes." (PMID 23865914, 2013). "There have been several reports of mutations in MYO15A causing hearing loss." (PMID 24206587, 2013). "MYO15A p.R2728H and MYO15A c.373delCG co-segregated with hearing loss in the family." (PMID 21917145, 2011). "In Saudi Arabia, several gene mutations (e.g., GIPC3, ILDR1, W77R, MYO15A, TMC1, TMPRSS3, and DFNB67) have been identified in families and are associated with childhood hearing loss." (PMID 40918669, 2025). "Multiple studies have demonstrated that the most common pathogenic variants associated with hearing loss are located within the motor, FERM, and MyTH4 domains of the MYO15A gene." (PMID 38167320, 2024). "Here, we report putatively novel variants in the genes MYO15A, MYO7A, and TECTA identified through genetic panel testing in children with hearing loss at birth or in early childhood." (PMID 39062005, 2024). "Other studies also indicated that, apart from GJB2, pathogenic variants in SLC26A4, MYO15A, OTOF, and CDH23 are a frequent cause of hearing loss in European populations (Hilgert, Smith, Van Camp, 2009)." (PMID 39498320, 2024). "Our findings are consistent with previously reported pathogenic variants in the MYO15A and OTOF genes in Middle Eastern individuals and suggest their implication in hearing loss." (PMID 37189200, 2023). "FOXI1, NF2, MYO15A and CLIC5 genes, were among others associated with swimming impairment and hearing loss." (PMID 34829759, 2021). "The hearing loss in four other patients was caused by pathogenic biallelic variants in the well-known hearing loss-causing genes: STRC (OMIM 606440); MYO15A (OMIM 602666); SLC26A4 (OMIM 605646); and LOXHD1 (OMIM 613072)." (PMID 34062854, 2021).
hearing loss (continued). "Myosin genes are known to be responsible for 10 types of syndromic as well as non‐syndromic hearing loss (MYO7A, DFNA11/DFNB2/USH1B; MYH9, DFNA17; MYH14, DFNA4; MYO6, DFNA22/DFNB37, MYO3A, DFNB30; MYO15A, DFNB3)." (PMID 32027099, 2020). "Our findings further extended the pathogenic variants of MYO15A gene in the ARNSHL group and would have a positive implication in genetic counseling for hearing loss families." (PMID 29849560, 2018). "In particular, GJB2, SLC26A4, MYO15A, OTOF, and CDH23 are the most common genes responsible for hereditary hearing loss." (PMID 30068307, 2018). "Mutations in the MYO15A, OTOF, TMC1 and other genes have emerged as being among the more prevalent nonsyndromic hearing loss mutations, worldwide." (PMID 20668687, 2010). "Notably, mutations in MYO15A, which are known to cause non-syndromic deafness (DFNB3; OMIM #600316), have been identified in SMS patients with hearing impairment." (PMID 40724914, 2025). "Studies of iPSCs from MYO15A and MYO7A mutation patients demonstrate the feasibility of generating inner ear hair cells from human iPSCs and the functional rescue of gene mutation-caused hearing loss by using genetic correction." (PMID 38167128, 2024). "Known pathogenic variants in MYO15A, GJB2, and USH2A were most likely to be causal of hearing loss." (PMID 39062005, 2024). "Potential causative variants were identified in genes associated with nonsyndromic hearing loss (CIB2, COL11A1, ILDR1, MYO15A, TMPRSS3, and WFS1), nonsyndromic hearing loss or Usher syndrome (CDH23, MYO7A, PCDH15, and USH2A), and other syndromic forms of hearing loss (CHD7, OPA1, and SPTLC1)." (PMID 34837038, 2022). "In fact, the MYO15A gene, which is a causative gene of DFNB3 (OMIM 600316) and has been known to be associated with moderate to severe hearing loss as well as profound hearing loss, is usually ranked as the third or fourth most common cause of DFNB deafness in many ethnicities." (PMID 30733538, 2019). "MYO15A, which encodes a myosin expressed in the cochlea, harbors many mutations worldwide responsible for hearing loss, but neither MYO15A p.R2728H nor MYO15A c.373delCG has been described previously." (PMID 21917145, 2011). "The proband (II.1) underwent genetic testing using a high throughput NGS panel for 60 known pathogenic variants that cause hearing loss, which revealed a heterozygous synonymous variant in MYO15A (c.9861C>T; p.Gly3287Gly), but no second MYO15A pathogenic allele." (PMID 34733312, 2021). "However, recent advances in NGS technology have facilitated mutation detection and confirmed MYO15A mutations as a common cause of autosomal recessive non-syndromic hearing loss in several populations." (PMID 31581539, 2019). "Novel mutations were identified in multiple other genes - CDH23, MYO15A, WFS1, and TECTA - that are known to be responsible for hearing loss but are not routinely evaluated, largely because of their size." (PMID 21917145, 2011).
autosomal recessive deafness (10 papers, 2013 to 2025). "Mutations of MYO15A at the DFNB3 locus appear to be the third or fourth most common cause of autosomal recessive nonsyndromic deafness." (PMID 29692870, 2018). "Members of the myosin superfamily (MYO7A, MYO15A, and MYO6) are involved in voice conduction, but variants in MYO15A are now considered to be one of the most common causes of nonsyndromic autosomal recessive hearing loss (ARNSHL)." (PMID 31250571, 2019). "However, some studies from the United States, Belgium, Northern Europe, and East Asia indicated that pathogenic variants in SLC26A4, MYO15A, OTOF, and CDH23 are probably the most common causes of autosomal recessive hearing loss, after the exclusion of variants in the DFNB1 locus." (PMID 39498320, 2024).
Usher syndrome (6 papers, 2011 to 2025). A syndromic diseae characterized by the association of sensorineural deafness (usually congenital) with retinitis pigmentosa and progressive vision loss. "MYO15A mutations are associated with the Usher syndrome having affected hearing." (PMID 37672513, 2023). "Another patient (P49) with Usher syndrome was found to carry LP variants in the ADGRV1 gene, in addition to two LP/VUS variants in the MYO15A gene." (PMID 41000418, 2025).
nonsyndromic hearing loss (4 papers, 2013 to 2024). "It is well established that pathogenic variants in MYO15A underlie autosomal recessive nonsyndromic hearing loss at the DFNB3 locus." (PMID 34733312, 2021).
cerebral malaria (1 paper, 2014). A sequestration of Plasmodium falciparum in the brain, which can cause coma and/or seizures. "Moreover, myosin 15A (MYO15A) was increased in the CM group similarly to the ‘cerebral malaria’ cluster components of the ‘targeted array’." (PMID 24743550, 2014).
cognitive decline (1 paper, 2025). "Higher levels of NNT, MYO15A, and GCA were protective in females; greater expression of PEPD, CTNNBL1, MVB12A, XKR8, WBP1L, and GALNT7-DT were associated with faster cognitive decline in females." (PMID 40166028, 2025).